CXCL9 (C-X-C motif chemokine ligand 9)
Diseases named in the same sentence as CXCL9 in open-access papers (continued):
Sharing a sentence is not in itself a finding about the gene and the disease.
sarcoidosis (continued). "Interferon-γ–inducible chemokines, CXCL9 and CXCL10, are elevated in sarcoidosis and inter-correlated with each other." (PMID 24199653, 2013). "We found that CXCL9 and CXCL10 were indeed elevated in the serum of sarcoidosis subjects compared to controls and further, found that their levels correlated with the lung function measurements DLCO and FVC, respectively." (PMID 24199653, 2013). "Reanalysis of a sarcoidosis scRNA-seq dataset revealed that, similar to NL and NXG, sarcoidosis lesional fibroblasts expressed high levels of MHC (e.g., HLA-B and HLA-DRA), CD74, PLOD2, STAT1, TNC, PRSS23, PSMB9, and CXCL9." (PMID 39989459, 2025). "It has been reported that alveolar macrophages from sarcoidosis patients secreted large amounts of CXCR3 ligands, including CXCL9, CXCL10, and CXCL11, that could play crucial roles in the accumulation of Tregs in the site of inflammation." (PMID 37189479, 2023). "When comparing to control subjects, the expression levels of CC chemokines CCL3 (P = 0.043), CCL4 (P = 0.034), CCL5 (P < 0.001), and CCL8 (P = 0.031) and CXC chemokines CXCL9 (P < 0.001), CXCL10 (P = 0.002), and CXCL11 (P = 0.008) were found to be elevated in sarcoidosis patients." (PMID 26696750, 2015). "Induction of CXCR3 with CXCL9 and/or CXCL10 allows for T cell migration into organ tissues, including those that are typically thought of as immune privileged, and contributes to Th1 cell differentiation, which are common features of sarcoidosis." (PMID 24199653, 2013). "In summary, we found that serum CXCL9 and CXCL10 levels correlated with sarcoidosis disease severity as assessed by FVC and DLCO, as well as the Wasfi severity score, which incorporates additional clinical phenotypes of sarcoidosis." (PMID 24199653, 2013). "Our findings in the peripheral blood, along with data from several other cross-sectional BALF studies, suggest that CXCL9 and CXCL10 may play important roles in the pathogenesis of sarcoidosis." (PMID 24199653, 2013). "In a cross-sectional analysis of 36 non-immunosuppressed sarcoidosis subjects, serum CXCL9, CXCL10, and sIL2R were significantly elevated compared to 46 controls (p < 0.0001)." (PMID 24199653, 2013). "However, the dissociation of CXCL9 and CCL5 expression in sarcoidosis fibroblasts is not surprising because different external cytokine stimuli are required to induce CXCL9 and CCL5 expression in fibroblasts." (PMID 39989459, 2025). "Thus, while CD74- and CXCL9-expressing inflammatory fibroblasts are present in sarcoidosis, their phenotype does not perfectly match the CCL5hi fibroblasts seen in NL and NXG fibroblasts." (PMID 39989459, 2025).
asthma (13 papers, 2013 to 2025). "With Mendelian randomization, key cytokines like G-CSF/CSF-3 and CXCL9/MIG are identified as potential causal mediators of asthma and Crohn’s disease, respectively." (PMID 39794498, 2025). "We used the assay to evaluate serum samples from patients with asthma, ILDs, and HP to define the association between serum CXCL9 levels and chronic respiratory diseases." (PMID 37005469, 2023). "Drug target cis-MR using 2 independent proteomics datasets paired with colocalization revealed G-CSF/CSF-3 and CXCL9/MIG as potential causal mediators of asthma and Crohn’s disease, respectively, but also a potentially protective role of TNF-b in multiple sclerosis." (PMID 39794498, 2025). "Elevated serum CXCL9 levels have been reported in patients with asthma, interstitial lung disease (ILD), and COVID-19 infection." (PMID 40313944, 2025). "To define the relationship between CXCL9 levels and other inflammatory parameters, we compared CXCL9 levels with those of several cytokines in samples from patients with asthma." (PMID 37005469, 2023). "We identified high serum CXCL9 levels in samples from patients with acute COVID-19 infections (n = 57), chronic bird-related hypersensitivity pneumonitis (n = 61), asthma (n = 194), and ILDs (n = 84) compared to healthy individuals (< 39.0 pg/mL)." (PMID 37005469, 2023). "Serum CXCL9 levels in asthma patients are positively correlated with CXCL10 and CXCL11 levels, which are also CXCR3 ligands." (PMID 37005469, 2023). "Serum CXCL9 levels are reportedly elevated in some patients with asthma, interstitial lung diseases (ILDs), contact dermatitis, severe drug eruption, autoimmune diseases, and viral infections." (PMID 37005469, 2023). "We found that serum CXCL9 levels increased with age in patients with asthma, whereas serum IL-4 and total IgE levels showed an inverse trend relative to CXCL9 levels." (PMID 37005469, 2023). "In a mouse model of asthma, treatment with exogenous CXCL9 significantly reduced airway hyper-responsiveness and eosinophil recruitment." (PMID 27727269, 2016). "In vivo and in vitro experiments have shown that CXCL9 can reduce the immune responses to challenge with certain antigens in asthma." (PMID 27727269, 2016). "Using cis-acting variants for G-CSF/CSF-3, CXCL9/MIG, and TNF-b from the UKBB proteomics dataset as instruments, we could confirm significant associations with asthma, CD, and MS, respectively." (PMID 39794498, 2025). "Furthermore, the percentage of childhood-onset asthma was only 7.5% among patients aged > 60 years, with most having higher CXCL9 levels compared to HCs." (PMID 37005469, 2023). "However, CXCL9 levels in patients with asthma and ILDs were higher than the levels in normal samples, and the difference among the age classes in the healthy subjects was extremely small compared to the disease condition." (PMID 37005469, 2023). "Furthermore, CXCL9 levels increased with age in asthma patients, and an opposite trend was observed for T2 inflammatory factors." (PMID 37005469, 2023). "However, present data suggest a relationship between serum CXCL9 levels and respiratory inflammation, whereas the opposite trend is observed in patients with Th2 asthma." (PMID 37005469, 2023). "In patients with asthma, CXCL9 levels negatively correlated with IL-4 levels." (PMID 37005469, 2023). "However IFN-regulated chemokines Cxcl9 and Cxcl10, both of which have been observed in the airways of patients with severe asthma, were reduced following miR-155-5p and miR-99a-5p inhibition." (PMID 33846533, 2021). "These included associations of higher genetically proxied G-CSF/CSF-3 levels with asthma, lower genetically proxied G-CSF/CSF-3 and higher genetically proxied CXCL9/MIG levels with CD, as well as lower genetically proxied TNF-b levels with MS." (PMID 39794498, 2025).
asthma (continued). "For the inflammatory cytokines in the lung, the contents of TNF-α, TNFR2, CXCL-9, CCL-12, CCL-9, CCL-2, and CCL-5 in the asthma model group were higher than those in the control group, while the contents of GM-CSF and IL-1α were decreased." (PMID 35600943, 2022). "Ghebre reported that sputum CXCL9 level and serum CXCL11 level increased during asthma exacerbation." (PMID 35187081, 2022). "CXCL9 and CXCL10, which have been shown to be induced in other mouse models of asthma and A. fumigatus-induced inflammation (34, –, 36), activate Th1-type immune responses through CXCR3." (PMID 33597172, 2021). "Integrating our data with genetic and clinical data for human disease risk, our analyses suggest potential targets like G-CSF/CSF-3, CXCL9/MIG, and TNF-b for immune-related diseases including asthma, Crohn’s disease, and multiple sclerosis, warranting further exploration in clinical trials." (PMID 39794498, 2025). "In addition, the contents of TNF-α, TNFR2, CXCL-9, CCL-12, CCL-9, CCL-2, and CCL-5 in the asthma model group were higher than those in the control group, while the contents of GM-CSF and IL-1α were decreased." (PMID 35600943, 2022). "CXCL9, a chemoattractant for T lymphocytes, involving elements of mixed type 2 and non-type 2 bronchial inflammation in asthma, is upregulated by IFN-γ, a Th1 cytokine." (PMID 30834110, 2019). "Compared to healthy control subjects, patients with asthma had significantly more percentages of eosinophils and neutrophils, IL-1RA, IL-1α, IL-1β, IL-2Rα, IL-5, IL-6, IL-7, IL-8, G-CSF, GROα (CXCL1), MIP-1β (CCL4), MIG (CXCL9), RANTES (CCL5) and TRAIL in their BAL fluids." (PMID 26011707, 2015). "Interestingly, in the non-atopic asthma group, FeNO, MMP-1, and CXCL9 all inter-correlated, whereas this was not seen in atopic asthmatics." (PMID 30834110, 2019).
breast tumors (13 papers, 2012 to 2025). "CXCL9 has been reported to be associated with promoted intratumour infiltration of immune cells in breast tumours and can be used for predicting therapeutic response." (PMID 34527583, 2021). "Therefore, SRC-3 inhibition activates the Cxcl9/Cxcr3 axis, causing an antitumor immune microenvironment by recruiting cytotoxic immune cells into breast tumors." (PMID 36316775, 2022). "More specifically, our study demonstrates that aged human and mouse breast tumor cells produce lower levels of the T cell–attracting chemokines CXCL9 and CXCL10." (PMID 41332581, 2025). "Mechanistic studies in in vitro and in vivo ADCC models indicate the importance of NK cells for the initial production of CCL5/IFN-ɣ, subsequently resulting in CXCL9/10 production by bystander breast tumor cells, during anti-HER2 antibody treatment." (PMID 38167224, 2024). "ACT with SRC-3 KO Tregs also significantly increased Ifng and Cxcl9 in breast tumors compared to ACT with wild-type Tregs." (PMID 37253006, 2023). "To further validate our results in the bioinformatics analysis, we sought to determine the levels of CXCL9 in breast tumours and analyse its relevance to ER status, PR status and other clinicopathological features." (PMID 34527583, 2021). "Our findings provide a mechanistic link between the COX pathway and CXCL9/CXCL10 chemokine secretion into the tumor microenvironment of human breast tumors." (PMID 22333315, 2012). "Therefore, the activated Ifng/Cxcl9 axis stimulated by SRC-3 KO Tregs would be expected to suppress WT Tregs in breast tumors by enhancing Ifng-induced cellular fragility in WT Tregs." (PMID 37253006, 2023). "Therefore, SI-2-mediated SRC-3 inhibition increased the levels of Cxcl9 in breast tumors to recruit cytotoxic immune cells." (PMID 36316775, 2022). "To approach our hypothesis that the COX system will have a significant impact on the CXCR3 ligand milieu of breast tumor environment we first investigated the effect of exogenous PGE2 on CXCL9 and CXCL10 release." (PMID 22333315, 2012). "In this case, we showed that downregulation of CXCL9/10 is a feature of both mouse and human HER2+ breast tumors, supporting the tumor-promoting role of aging." (PMID 41332581, 2025). "This appears to be the case in the present studies where IOA-289 decreased the plasma concentrations of CCL2, CXCL9, and CXCL10, together with its effect of inhibiting the growth of E0771 breast tumors." (PMID 37296899, 2023). "The secreted CXCL9 and CXCL10 bind to CXCR3 on the surface of a subpopulation of breast tumour cells, which promotes initiation and growth of metastatic tumour cells." (PMID 35869057, 2022). "IHC analysis revealed that Cxcl9 levels were elevated in SI-2-treated E0771 breast tumors and SRC-3 KD E0771 breast tumors compared with their control breast tumors." (PMID 36316775, 2022). "A mouse cytokine array revealed that Cxcl9 levels were significantly increased in SRC-3 KD E0771 breast tumors and SI-2-treated E0771 breast tumors compared to control breast tumors." (PMID 36316775, 2022). "Notably, the C-X-C motif chemokine ligand 9/10/11 (CXCL9/10/11)- C-X-C motif chemokine receptor 3 axis, which relies on IFN-γ activity, is highly expresse in primary breast tumors from patients with subsequent brain metastases." (PMID 41220920, 2025). "Thus, Ifng from SRC-3 KO Tregs elevates Cxcl9 expression in E0771 breast tumors in SRC-3d/d:Treg female mice and suppresses the growth of breast tumors." (PMID 37253006, 2023). "Furthermore, Il-16 (2.7-fold) and C-X-C motif chemokine ligand 9 (Cxcl9, ninefold) levels were significantly increased in SRC-3 KD E0771 breast tumors compared to control breast tumors." (PMID 36316775, 2022). "However, immune cells also produce Cxcl9, Il-1ra, and Il-16, while it is not clear whether SRC-3 KD breast tumors express these cytokines." (PMID 36316775, 2022).
multiple sclerosis (13 papers, 2012 to 2025). A progressive autoimmune disorder affecting the central nervous system resulting in demyelination. "CXCR3 is abundantly expressed on CNS-infiltrating T cells in multiple sclerosis patients and coordinates CNS-directed T cell migration in response to its three ligands, CXCL9/CXCL10/CXCL11." (PMID 38349430, 2024). "CSF levels of TNF-α, CXCL9, and IL-6 are also elevated in other neuroinflammatory diseases such as multiple sclerosis." (PMID 37304071, 2023). "CXCL9 is secreted in high levels in chronic inflammatory and auto-immune diseases, such as human T cell lymphotropic virus infection and multiple sclerosis." (PMID 22458474, 2012). "In particular, people with multiple sclerosis on natalizumab had lower CD6, CDCP1, CXCL13, CXCL9, NfL, TNFRSF10a, TNFSF13B and VCAN (P < 0.036)." (PMID 37361716, 2023). "CCR5 is commonly expressed by intrathecal Th lymphocytes in both infectious (neuroborreliosis) and non-infectious (multiple sclerosis, MS) cns inflammation, usually alongside CXCR3 receptor for chemokines CXCL9 and CXCL10, but its role remains debatable." (PMID 26906062, 2016).
non-small cell lung carcinoma (13 papers, 2020 to 2026). A group of at least three distinct histological types of lung cancer, including non-small cell squamous cell carcinoma, adenocarcinoma, and large cell carcinoma. "For the first time, this study introduces the CXCL9/SPP1 polarity axis into the field of non-small cell lung cancer (NSCLC)." (PMID 42079623, 2026). "A study on non-small cell lung cancer demonstrated that CXCL9, a protein marker, could predict the prognosis of immunotherapy based on PD-1/PD-L1 blockade." (PMID 38957805, 2024). "It has been demonstrated that high expression of CXCL9 in human early stage non-small cell lung cancer, recombinant human cytokine CXCL9 (rhCXCL9), or ligand transfer of CXCL9 can inhibit tumor-derived angiogenesis and suppress the growth and metastasis of tumor cells." (PMID 36479091, 2022). "This is consistent with previous studies that reported that a lower expression of CXCL9 among several genes could be an early prognostic factor in HNSCC and non-small-cell lung cancer." (PMID 38067251, 2023). "Finally, elevated pre-treatment CXCL9 and CXCL10 levels appear to correlate with the response to anti-PD1 therapy in patients with non-small cell lung cancer." (PMID 37569757, 2023).
pulmonary fibrosis (13 papers, 2016 to 2025). Chronic progressive interstitial lung disorder characterized by the replacement of the lung tissue by connective tissue, leading to progressive dyspnea, respiratory failure, or right heart failure. "In patients with pulmonary fibrosis, increased levels of CXCL9, CXCL10, CCL18, CTO, and CA15.3 are accompanied by elevated SP-D, a component of lung surfactant and a pattern-recognition molecule produced by alveolar type II cells and Clara cells." (PMID 37445972, 2023). "Our findings are consistent with the suppression of CXCL-9 by IL-22 in an animal model of lung fibrosis which limited recruitment of CD4+CXCR3+ T cells and attenuation of lung inflammation and fibrosis." (PMID 29163483, 2017). "In that study, IL-22 protects against lung fibrosis by suppressing the CXCL9-dependent recruitment of CD4+ T cells into the lung." (PMID 27650379, 2016). "CCL17 plays an important role in the pathogenesis of pulmonary fibrosis and CXCL9 may have an antifibrotic effect in chronic bird-related HP." (PMID 31369605, 2019). "Then, drawing from previous evidence that Th2-predominant immune response may play an important role in the development of lung fibrosis in chronic HP, we also analyzed serum levels of CXCL9 (Th1 chemokine), CCL17 (Th2 chemokine), and Krebs von den Lungen 6 (KL-6)." (PMID 31369605, 2019). "Like CCL5 and CXCL9, MDK is a profibrotic cytokine, demonstrated by its role in murine models of pulmonary fibrosis and its use as a biomarker in idiopathic pulmonary fibrosis." (PMID 39989459, 2025). "Multiple studies have shown that chemokines such as CXCL9, CXCL10, and CXCL11 promote pulmonary fibrosis by recruiting fibrosis-related macrophages, but the role of CXCL14 in IPF has long been overlooked." (PMID 40842541, 2025). "We found in this model that circulating levels of CXCL9, DKK3, and MMP3 were already significantly elevated in day 18 samples, on average 10 days before the diagnosis of cGVHD, including pulmonary fibrosis." (PMID 37526081, 2023). "Studies have demonstrated an imbalance in the levels of angiogenic chemokines (ELR+ CXC chemokines [CXCL5 and CXCL8]) and angiostatic chemokines (interferon-inducible ELR- CXC chemokines [CXCL9, CXCL10, CXCL11]) in animal models of pulmonary fibrosis and lung tissue from patients with IPF." (PMID 39418259, 2024). "The serum levels of CXCL9 and CXCL10 were higher in anti-Jo-1 antibody-positive DM-ILD patients than in those with idiopathic pulmonary fibrosis, which distinguished this disease entity from idiopathic pulmonary fibrosis and anti-signal recognition particle antibody-positive myositis." (PMID 34938325, 2021). "Finally, group IV comprised several mediators of pulmonary fibrosis as IL-8/CXCL8, monocyte chemoattractant protein-1 (MCP-1)/CCL-2, monokine induced by IFN-γ (MIG)/CXCL9 and fibroblast growth factor-(FGF)-9, highly expressed in IPF patients but not in the other two groups." (PMID 38111019, 2023). "Interestingly, both CXCL9 and CXCL10 but not CXCL8, exert their effects via chemokine receptor CXCR3, and CXCR3-deficient mice are known to develop progressive interstitial pulmonary fibrosis." (PMID 27127180, 2016).